CDK6 (cyclin dependent kinase 6)
Diseases named in the same sentence as CDK6 in open-access papers (continued):
Sharing a sentence is not in itself a finding about the gene and the disease.
colorectal cancer (42 papers, 2012 to 2025). A primary or metastatic malignant neoplasm that affects the colon or rectum. "Here, we found circular RNA hsa_circ_000984 encoded by the CDK6 gene was remarkably upregulated in the tissues of colorectal cancer (CRC) patients and in the CRC cell lines." (PMID 29207676, 2017). "Given the established role of cyclin-dependent kinases (CDKs) and cyclins in cell cycle regulation, we examined the expression of cyclin D1, cyclin E1, and CDK6 in colorectal cancer cells treated with CS&Z extract." (PMID 40429805, 2025). "The miR-584 was found in the SW620 colorectal cancer cell line to interfere with binding of hnRNP A1 and CDK6." (PMID 38632250, 2024). "Previous studies have shown that GPR37 can interact with CDK6, influence the tumor progression of lung adenocarcinoma, and promote metastasis in colorectal cancer through the Hippo pathway." (PMID 39730361, 2024). "In conclusion, DDX39B acts as a colorectal cancer promoter through its effect on the CDK6/CCND1, which can promote the G1/S phase transition to enhance CRC proliferation." (PMID 35046400, 2022). "This phenotype demonstrated that not only overexpression of DDX39B can promote the proliferation of the colorectal cancer cells but also that can be reversed after knockdown of the CDK6 and CCND1." (PMID 35046400, 2022). "The prior studies have revealed that Cyclin D1 and CDK6 were abundantly expressed in colorectal cancer and have attracted much attention in multiple areas of cancer research and prognosis judgement." (PMID 33726765, 2021). "Previous research has also shown that mafb deprivation destroys direct downstream regulator cyclin-dependent kinase 6 (CDK6) transcription and impedes clinical colorectal cancer (CRC) cell proliferation, as a result of the cell cycle arrest at the G0/G1 phase." (PMID 34829928, 2021). "Generating a model of Palbociclib-resistant RASMUT colorectal cancer cells, we observed an increased expression of p27kip1, cyclin D, CDK4 and CDK6, coupled with an increased association between p27kip1 and CDK4." (PMID 34654798, 2021). "Among all the CDKs, including CDK1, CDK2, CDK4, and CDK6, CDK4 was defined as an independent risk factor for colorectal cancer." (PMID 34595111, 2021). "The results revealed that Cyclin D1, Cyclin D2, CDK4 and CDK6 were all decreased in si-SNHG1-transfected colorectal cancer cells." (PMID 30266084, 2018). "miR-129 can regulate multiple tumor cell lines and primary tumors including medulloblastoma, undifferentiated gastric cancers, lung adenocarcinoma, endometrial cancer and colorectal carcinoma through down-regulating CDK6 expression." (PMID 25707620, 2015). "The data suggest that CDK6 plays a critical role in RB phosphorylation and cell growth in colorectal carcinoma cells." (PMID 24765199, 2014). "The data presented herein have shown that the G1 phase cyclin D1, D2, D3, CDK4, CDK6 and pRB proteins are highly expressed in colorectal carcinoma tissues as compared to the matched adjacent normal colorectal tissues." (PMID 24765199, 2014). "Both CDK6 and RB are required for the cell cycle progression of colorectal carcinoma cells and by inhibiting the CDK6-RB axis, PD-0332991 induces the G1 cell cycle arrest and inhibits cancer cell growth." (PMID 24765199, 2014). "In this study, we showed that CDK6 and RB are highly expressed in colorectal carcinoma tissues and derived cells as compared to the matched normal colorectal tissues." (PMID 24765199, 2014). "This study therefore suggests that PD-0332991 has therapeutic effects against colorectal carcinomas through inhibition of the CDK6/RB pathway." (PMID 24765199, 2014). "The results revealed dose-dependent and time-dependent reductions in the expression of a range of cell cycle proteins, including cyclin E1, cyclin D1, and CDK6, accordingly indicating that CS&Z can influence the progression of the cell cycle in colorectal cancer cells." (PMID 40429805, 2025).
colorectal cancer (continued). "Hence, 4i analog is the first nortopsentin analog that acts as antitumor agent against colorectal carcinoma via inhibiting CDK6 at both transcriptional and enzymatic activity levels." (PMID 39487179, 2024). "Mechanistically, hsa-circ-101555 was identified as a “sponge” of miR-597-5p whose target is the cell cycle regulator CDK6, indicating that hsa-circ-101555 may act as a competitor of miR-595-5p in upregulating CDK6 expression in colorectal cancer." (PMID 34771517, 2021). "The results demonstrated that, by targeting of CDK6-RB axis, PD-0332991 may prove to be a novel therapeutic agent in treating colorectal carcinoma." (PMID 24765199, 2014). "The aim of this study was to determine whether CDK4, CDK6 and phosphorylated RB proteins were overexpressed in colorectal carcinoma tissues as compared to matched normal colorectal tissues." (PMID 24765199, 2014). "By contrast, the mechanism underlying the regulatory effects of CDC42EP3 on colorectal cancer were demonstrated through the detection of cancer-related signaling including Akt, CDK6, Cyclin D1 and PIK3CA, a reflection of the downregulation of Akt, p-Akt, CDK6, Cyclin D1 and PIK3CA." (PMID 33726765, 2021). "However, it remains unclear whether CDK4, CDK6 or both are required for RB phosphorylation in colorectal carcinoma and thus PD-0332991 can be used to target this CDK-RB axis for the cancer therapy." (PMID 24765199, 2014). "However, whether CDK4, CDK6 or both are required for the G1-S transition of colorectal carcinoma cells remains to be clarified." (PMID 24765199, 2014). "However, whether CDK4 or CDK6 or both were required for RB phosphorylation and G1-S transition in colorectal carcinoma cells remained to be clarified." (PMID 24765199, 2014). "In colorectal cancer models, analog 4i—a nortopsentin derivative—exhibited particularly potent activity, downregulating CDK2, CDK4, and CDK6 expression and suppressing CDK6 enzymatic activity to induce G1-phase arrest." (PMID 40710508, 2025). "4i induced cell cycle arrest in colorectal carcinoma through downregulating the expression of CDK2, CDK4 and CDK6." (PMID 39487179, 2024). "In summary, this important finding further emphasized DDX39B can directly bind to its downstream CDK6 and CCND1 genes and upregulate their expression levels to promote the proliferation of the colorectal cancer cells." (PMID 35046400, 2022). "And our study focused on the mechanism of DDX39B in the proliferation of colorectal cancer, we found that DDX39B can bind directly to the exons of CCND1/CDK6 mRNA to upregulate their expression and promote the CRC cell proliferation as an oncogene." (PMID 35046400, 2022). "The induction of miR-26a or miR-584 inhibited the binding between hnRNP A1 and CDK6 mRNA, which is recognized and stabilized by hnRNP A1 mediating RBD, and decreased CDK6 expression, resulting in apoptosis induction in colorectal cancer cells." (PMID 34830186, 2021).
prostate carcinoma (41 papers, 2012 to 2026). A carcinoma that arises from epithelial cells of the prostate gland. "Beyond its established role in G1 cell cycle progression, CDK6 has been implicated in the stimulation of AR activity, potentially contributing to prostate cancer development and progression." (PMID 40304827, 2025). "These included a gain of chromosomes 3 and 7, with CDK6 (cyclin-dependent kinase 6) being involved, and a loss of the arms of chromosomes 8p, 10p, and 12p, all of which are frequently seen in prostate cancer." (PMID 40606443, 2025). "The CRIPSCs also expressed prostate stem cell antigen (Psca) and cyclin-dependent kinase 6 (Cdk6); the latter can associate with AR and enhance its transcriptional activity in prostate cancer cells." (PMID 35841025, 2022). "In giant cell carcinoma and prostate carcinoma cells, berberine also decreased G0/G1 phase-associated cyclins (D1, D2, E, Cdk2, Cdk4, and Cdk6), inducing G0/G1 arrest and suppressing cell proliferation." (PMID 23213296, 2012). "In our interaction network, CDK6 was targeted by 14 miRNAs validated in prostate cancer, including the network hub hsa-miR-16-5p." (PMID 41598250, 2026). "In this study, we aimed to estimate the contribution of these selected polymorphisms (CDK4 rs2069502, CDK6 rs2285332, CCND1 rs9344, p16INK4a rs11515, p15INK4b rs3217986, RB rs3092904) within the cyclin D-CDK4/6-INK4-RB pathway to prostate cancer risk." (PMID 40304827, 2025). "We evaluated CDK4 rs2069502, CDK6 rs2285332, CCND1 rs9344, p16INK4a rs11515, p15INK4b rs3217986, and RB rs3092904 polymorphisms using TaqMan® SNP Assays in a cohort comprising 532 prostate cancer patients and 567 control subjects." (PMID 40304827, 2025). "In this study, we found that MA inhibits the expression of CDK2, CDK4, and CDK6 and enhances that of p27, Rb and p-Rb to block G1/S transition in the cell cycle of prostate cancer cells." (PMID 39624845, 2024). "CDK4/CDK6 inhibitors have also been shown to exert synergistic anticancer effects with BRD4 inhibitors in castration-resistant prostate cancer and NUT midline carcinoma." (PMID 38135679, 2023). "Simvastatin and lovastatin suppressed expression of CDK1, CDK2, CDK3, CDK4, and CDK6 in prostate cancer cells with reduced cell viability due to induced apoptosis and cell cycle arrest." (PMID 36946734, 2023). "miR-105 from tumor-derived exosomes functions as a tumor suppressor and prevents cell proliferation in prostate cancer by targeting cyclin-dependent kinase 6 (CDK6)." (PMID 33805398, 2021). "Subsequently, upregulation of Cyclin D1 and CDK6 was also partially reversed by MK-2206, which served as an evidence for the involvement of Akt/Cyclin D1/CDK6 pathway in prostate cancer." (PMID 33902600, 2021). "Cyclin D1 and CDK6, as the other two important regulators in cell cycle and cell proliferation, have been demonstrated to be highly expressed in prostate cancer and have enormous potential in wide various of cancer research and prognosis judgement." (PMID 33902600, 2021). "Knockdown of PSMC2 gave rise to the blocked development and metastasis of prostate cancer, which was probably resulted from regulating Akt/Cyclin D1/CDK6 signalling pathway." (PMID 33902600, 2021). "This indicated the potential involvement of the Akt/Cyclin D1/CDK6 pathway in the PSMC2-induced proliferation of prostate cancer." (PMID 33902600, 2021). "In prostate cancer, androgen receptor-dependent transcription is stimulated by direct binding of CDK6." (PMID 33255177, 2020). "Another member of the CDK family, CDK6, also stimulates AR transcriptional activity in prostate cancer cells." (PMID 28262798, 2017). "Expression of CDK6 markedly enhanced activation of the luciferase reporter in the presence of the AR in PC3 human prostate cancer cells." (PMID 28262798, 2017). "Hono also caused cell cycle arrest by decreasing the expression of cell cycle-related proteins, such as cyclin D1, CDK4 and CDK6 in PC-3 prostate cancer cells." (PMID 27074557, 2016).
prostate carcinoma (continued). "Although SHP-1 has been demonstrated to be an inhibitor of cell proliferation, knockdown of SHP-1 was recently reported to downregulate CDK6 and inhibit G1/S progression in prostate cancer cells." (PMID 25109634, 2014). "Although SHP-1 was demonstrated to be a negative regulator of proliferation, knockdown of SHP-1 resulted in CDK6 downregulation and G1/S cell cycle arrest in prostate cancer cells." (PMID 25109634, 2014). "Within the prostate-associated protein subset, CDK6 was the most connected node (14 edges), followed by ACVR2B, KMT2A, and PIK3R1, each with 13 edges (which ranks potential biomarkers and their impacts in prostate cancer)." (PMID 41598250, 2026). "Moreover, the involvement of PSMC2 in prostate cancer was mediated by the activity of Akt/Cyclin D1/CDK6 signaling pathway." (PMID 33902600, 2021). "Collectively, these results indicated that PSMC2 may promote the development of prostate cancer by regulating the Akt/Cyclin D1/CDK6 pathway." (PMID 33902600, 2021). "Our experimental data might provide a strategy for targeting with the PSMC2/Akt/Cyclin D1/CDK6 signalling pathway interaction as a novel therapeutic application to treat prostate cancer patients." (PMID 33902600, 2021). "Overexpression of CDK6 thereby contributes to prostate cancer progression." (PMID 33255177, 2020). "Our data suggest concurrent targeting of BMI1 and CDK4/CDK6 might provide novel therapeutic opportunity for breast, colon, and prostate cancer." (PMID 31548560, 2019). "Silibinin has been reported to inhibit cell growth and induce G1 arrest in cell cycle progression of human prostate carcinoma, which was associated with decreased levels of cyclin D1, CDK4, and CDK6 and induction of Cip1/p21 and Kip1/p27, followed by increased binding with CDK2." (PMID 28030611, 2016). "There is a single report that the CDK6 protein is part of a complex that binds DNA in an androgen receptor-dependent manner to enhance transcription of the prostate-specific antigen in LNCaP prostate cancer cells." (PMID 23948297, 2013). "However, the potential associations between other polymorphisms – such as CDK4 rs2069502, CDK6 rs2285332, p16INK4a rs11515, p15INK4b rs3217986, RB rs3092904 – and prostate cancer risk have not yet been elucidated." (PMID 40304827, 2025). "In addition, miR-186 decreases the CDK6 level to inhibit the prostate cancer cell growth." (PMID 36755807, 2023). "Moreover, the regulation of prostate cancer by PSMC2 may be mediated by Akt/Cyclin D1/CDK6 signaling pathway." (PMID 33902600, 2021). "Thus, inhibition of cyclin D1 and E and cdk2, cdk4 and cdk6 suggests that PM might inhibit proliferation by arresting prostate cancer cells in G1-phase." (PMID 25175770, 2014). "The relative mRNA expression levels of CDK4, CDK6, CCND1, p16INK4a, p15INK4b, and RB were assessed in 44 prostate cancer tissues and 31 BPH tissues using qRT-PCR." (PMID 40304827, 2025). "Therefore, we hypothesized that polymorphisms of genes encoded cyclin-dependent kinase 4 and 6 (CDK4 and CDK6), cyclin D1 (CCND1), CDK inhibitors p16INK4a and p15INK4b, as well as the retinoblastoma protein (RB), could modulate prostate cancer risk and influence the corresponding mRNA levels." (PMID 40304827, 2025). "Herein we found that MA inhibits prostate cancer cell proliferation by decreasing CDK2, CDK4, and CDK6 expression and concurrently increasing p27, Rb, p-Rb expression." (PMID 39624845, 2024). "In prostate cancer, TTTY15 exhibits prominent upregulation in most tumor samples, exerting a pro-carcinogenic influence by sponging miRNA let-7, subsequently elevating CDK6 and FN1 expression." (PMID 38589454, 2024). "In enzalutamide-resistant prostate cancer cells, suppression of SLC25A17 led to delayed cell cycle progression and reduced protein expression of Cyclin D1 and CDK6." (PMID 38402166, 2024). "In prostate cancer, lncRNA TTTY15 acted as a ceRNA and negatively regulated miR-let-7 to promote expression of the target genes (CDK6, FN1)." (PMID 32587476, 2020).
prostate carcinoma (continued). "In prostate cancer, the roles of CDK4 and CDK6 remain less clear." (PMID 40304827, 2025). "The only exception was the negative correlations of CDK4 and CDK6 (r = −0.5) with prostate cancer." (PMID 33668805, 2021).
hepatocellular carcinoma (36 papers, 2011 to 2025). A malignant tumor that arises from hepatocytes. "The progression of hepatocellular carcinoma can be affected by the knockdown of the long noncoding RNA H19 (H19) in hepatocellular carcinoma cells, and the expression of H19 is associated with CDK6." (PMID 40486867, 2025). "In hepatocellular carcinoma (HCC), ZFP36 functions as a tumor suppressor by destabilizing oncogenic mRNAs such as PRC1, CCND1, and CDK6, which are implicated in cell cycle progression and tumor growth." (PMID 40361912, 2025). "Here, using a broad-spectrum chemical probe, the authors perform kinome screening and identify CDK6-mediated accumulation of cancer stem cells as a driver of lenvatinib (multitargeted tyrosine kinase inhibitor) resistance in hepatocellular carcinoma." (PMID 37872167, 2023). "DHX9 knockdown increased the protein and mRNA levels of CDK6, which consequently resulting in hepatocellular carcinoma development." (PMID 35600388, 2022). "LNC-UCID enhances the expression of CDK6 by binding to DHX9 in hepatocellular carcinoma, and promotes G1/S transformation and the growth of hepatocellular carcinoma." (PMID 35410446, 2022). "Eriocitrin was reported to induce S phase arrest and upregulate CDK6 in hepatocellular carcinoma cells." (PMID 33858512, 2021). "In a similar vein, DHX9 can also mediate CDK6 downregulation, thereby supporting the helicase’s tumor suppressive functions that are compromised in hepatocellular carcinoma (HCC) due to the overexpressed long noncoding (lnc) RNA lnc-UCID." (PMID 33437516, 2020). "For example, circ‐ZEB1.33 is highly expressed in hepatocellular carcinoma tissues, and by sponging miR‐200a‐3p, up‐regulates CDK6 levels, leading to the promotion of hepatocellular carcinoma proliferation." (PMID 32378344, 2020). "LncRNA NNT-AS1 up-regulates CDK6 to promote progression in hepatocellular carcinoma by targeting miR-363." (PMID 32982585, 2020). "In hepato-hepatocellular carcinoma, miR-1299 inhibits cell proliferation by targeting cyclin-dependent kinase 6, however there is limited information about miR-1299 in diabetes." (PMID 30093963, 2018). "Various studies showed that WIN55212-2 has pro-apoptotic effects and results in growth arrest and downregulation of cell cycle dependent kinases like cdk2, cdk4 and cdk6 in different tumor cell lines such as HepG2 hepatoma cells." (PMID 22204398, 2011). "Intriguingly, IGG may induce cytotoxic autophagy in hepatocellular carcinoma via directly binding to the N terminus of cyclin-dependent kinase 6 (CDK6) and promoting its subsequent degradation." (PMID 41323787, 2025). "In hepatocellular carcinoma, LINC00592 was associated with patient prognosis and could target the cold shock domain-containing E1 protein, CDK6, miR-122-5p, and epoxide hydrolase 1, promoting the proliferation of hepatocellular carcinoma cells." (PMID 36050740, 2022). "Functional assays revealed that NNT-AS1 could promote proliferation, weaken cell cycle arrest and alleviate apoptosis by competing with CDK6 for miR-363 binding in hepatocellular carcinoma." (PMID 32928135, 2020). "Circ-ZEB1.33 promotes the proliferation of human hepatocellular carcinoma (HCC) by sponging miR-200a-3p and upregulating the expression of CDK6." (PMID 32005118, 2020). "CHEK1, CDC25A, and CCNE1, together with CCND1, CCND3, CDK4, CDK6, BTRC, E2F3, and FOXK1, were previously identified as the targets of miR‐497∼195 cluster in hepatocellular carcinoma." (PMID 40548926, 2025). "Previous studies have shown that CDK6, CCND1 and CCNE1 play an important role in the proliferation of hepatoma cells." (PMID 34980127, 2022). "In human hepatocellular carcinoma (HCC), the circ-ZEB1.33-miR-200a-3p-CDK6 regulatory axis can regulate HCC cell proliferation." (PMID 32380777, 2020).
hepatocellular carcinoma (continued). "Accumulating data indicated that circRNA plays important roles in regulating many biological processes of the tumor, the present study is designated for exploring roles of the circ-ZEB1.33-miR-200a-3p-CDK6 regulating axis in human hepatocellular carcinoma (HCC)." (PMID 30123094, 2018). "For instance, miR-195 can bind the 3′UTRs of cyclin D1, CDK6, and E2F3, thereby suppressing cell proliferation in human hepatocellular carcinoma cells." (PMID 29426937, 2018). "It reported that has-miR-195-497 cluster was intracellular antagonists of BMP signaling pathway in bone cells in and targeting cell cycle proteins CDK6, CCNE1, CDC25A and CDK4 to regulated cell proliferation in human hepatocellular carcinoma cells." (PMID 27384321, 2016).